ALDH7A1 (aldehyde dehydrogenase 7 family member A1)
Diseases named in the same sentence as ALDH7A1 in open-access papers (continued):
Sharing a sentence is not in itself a finding about the gene and the disease.
schizophrenia (1 paper, 2024). A major psychotic disorder characterized by abnormalities in the perception or expression of reality. "Besides, PDE4A was related to heat shock protein B6 (HSPB6), aldehyde dehydrogenase 7A1 (ALDH7A1), A-kinase anchoring protein 1 (AKAP1), adrenoceptor beta 2 (ADRB2), SAG (an arrestin family member which desensitizes GPCR) and DISC1 (disrupted in Schizophrenia 1)." (PMID 38514754, 2024).
Stroke (1 paper, 2022). Sudden impairment of blood flow to a part of the brain due to occlusion or rupture of an artery to the brain. "Considering the importance of ALDH7A1 in both vitamin B6 and ethanol metabolism, we examined the potential correlations between the most common polymorphic locus in ALDH7A1 among East Asians (rs12514417; Lys439Gln missense variant allele frequency 12.9% in Asian), stroke, and alcohol consumption." (PMID 36258220, 2022). "Unlike ALDH2, the function of ALDH7A1 is not well understood and no literature has described its association with stroke so far." (PMID 36258220, 2022).
ZIKV infection (1 paper, 2017). "Further examination of the roles of metabolic control genes such as TERT, ALDH7A1, CREB5, EAPP, and NDUFA11 as they relate to ZIKV infection may provide further insights into ZIKV pathogenesis." (PMID 28442752, 2017).
cancer (31 papers, 2014 to 2025). A tumor composed of atypical neoplastic, often pleomorphic cells that invade other tissues. "Three non-cancer pathogenic mutations cluster at Glu427 (aldehyde binding region) of ALDH7A1 and two mutations with the same labels are located at Arg138 (glutamate binding region) of ALDH18A1." (PMID 37373306, 2023). "The role of ALDH7A1 in stellate cancer associate fibroblast using knock out mice will be investigated in the next study." (PMID 33537098, 2021). "Publically available cancer gene expression data was interrogated to identify a gene-expression signature associated with depletion of ALDH7A1." (PMID 30486822, 2018). "Most non-cancer diseases mutations are found in ALDH7A1 and ALDH18A1." (PMID 37373306, 2023). "Similarly, low ALDH7A1 expression is associated with a lower incidence of cancer recurrence and superior RFS and OS in surgically resected NSCLC patients." (PMID 36694633, 2023). "The roles of the different ALDH7A1 polymorphisms may vary, moreover, on account of different allele mutations and cancer types." (PMID 35613852, 2022). "Since ALDH7A1 is a susceptibility gene for osteoporosis and is believed to play a role in bone formation and maintenance as well as cancer metastasis, assessing these specific phenotypes in PDE patients (and, perhaps, their carrier parents) would be of particular interest." (PMID 25004007, 2014). "However, in the TCGA database, low ALDH7A1 expression was correlated with disorders of the metabolic-associated signaling pathways, and the cancer metastasis mechanism might arise through cancer metabolism because of ALDH7A1 mutations." (PMID 35613852, 2022). "However, role of ALDH7A1 in pancreatic stellate cell may be also important because stellate cell plays a role as a cancer associate fibroblast." (PMID 33537098, 2021). "In summary, Tan IIA enhances the effectiveness of hyperthermia in treating HCC by inhibiting ALDH7A1, thereby weakening the cancer cells’ defenses against heat-induced stress." (PMID 41173836, 2025). "Nevertheless, few studies have discussed the interaction among betel quid chewing, ALDH7A1 expression, and cancer metastasis." (PMID 35613852, 2022). "ALDH7A1 expression in tumor cells and in patients with advanced cancer status was lower than that in normal tissue and in patients with early-stage disease." (PMID 35613852, 2022). "Ki-67 positive cell (proliferation marker) of pancreas in KPC mice showed that Aldh7a1 knockout decreased proliferation of cancer cell." (PMID 33537098, 2021). "ALDH7A1 was abundant in cancer stem cells, and knockdown of ALDH7A1 enhanced NSCLC sensitivity to cisplatin." (PMID 33991070, 2021). "For example, in various cancers has been demonstrated that aldehyde dehydrogenase 7 family, member A1 (ALDH7A1) and lipase C, hepatic type (LIPC) expression is associated with negative and positive prognostic potency, respectively." (PMID 32509589, 2020). "In this study, we provide evidence for a role of ALDH isoform 7A1 (ALDH7A1) in human cancer, and link this to regulation of PPAR activity." (PMID 30486822, 2018). "Literature on the role of ALDH7A1 in cancer suggests a somewhat complex scenario, with different outcomes in cancers of different tissue origin." (PMID 30486822, 2018). "Computational pathway and gene set enrichment analysis was used to identify signaling pathways and cellular processes that were correlated with reduced ALDH7A1 expression in cancer." (PMID 30486822, 2018). "To ask how ALDH7A1 levels correlate with EGFR activity in these cancers, we used reverse-phase protein array data on EGFR phosphorylation, which provides a measure of EGFR pathway activation in the tumors." (PMID 30486822, 2018). "Within early and late stage groups, patients with low ALDH7A1 expression showed worse survival outcome: 5-year survival probability for the patients with late stage cancer and high ALDH7A1 expression was ~ 40% vs ~ 20% for patients with low ALDH7A1." (PMID 30486822, 2018).
cancer (continued). "On the other hand, our analysis of 17 cancer types, using TCGA RNAseq data showed that ALDH7A1 expression was lower in several cancer types and that lower expression correlated with poor clinical outcome for HCC and renal ccRCC." (PMID 30486822, 2018). "ALDH7A1 has been identified as a glycolysis-related gene in cancer, which may facilitate glycolysis and promote cell survival under stress conditions." (PMID 41173836, 2025). "Taken together, ALDH7A1 has the potential to be a clinically useful biomarker in cancers." (PMID 36694633, 2023). "Conversely, the prognostic role of ALDH7A1 in cancer is equivocal." (PMID 35613852, 2022). "Finally, several studies reported the importance of ALDH isoenzymes in cancers, and ALDH7A1 is a member of the ALDH superfamily." (PMID 35613852, 2022). "Finally, few studies have discussed the interaction between betel quid chewing, ALDH7A1 expression, and cancer metastasis." (PMID 35613852, 2022). "We raised a question how ALDH7A1 contributes to cancer progression." (PMID 33537098, 2021). "To extend these results, we tested ALDH7A1-depletion in several cancer cell lines." (PMID 30486822, 2018). "To date, little is known about the role of ALDH7A1 in cancer." (PMID 30486822, 2018). "ALDH7A1 mRNA was significantly lower in tumors from 7 cancers compared to normal tissue controls." (PMID 30486822, 2018). "If high ALDH7A1 expression is important for liver and kidney homeostasis, it is tempting to speculate that low expression of this enzyme might contribute to cancer development in these tissues to a greater extent than in other tissue types." (PMID 30486822, 2018). "Immunohistochemistry was used to assess ALDH7A1 expression in tissue samples from cancer patients." (PMID 30486822, 2018). "ALDH7A1 was identified as a potential cancer gene using a Drosophila in vivo metastasis model." (PMID 30486822, 2018). "However, the role of ALDH7A1 in cancer development and prognosis has remained unclear." (PMID 35613852, 2022). "Thus, the influence of ALDH7A1 on prognosis should be evaluated for individual cancer types." (PMID 35613852, 2022). "However, high ALDH7A1 expression can play an opposite role in other cancer types." (PMID 35613852, 2022). "Therefore, it is reasonable to consider that anti-cancer effect of ALDH7A1 knockdown or inhibition resides on blocking fatty acid oxidation through inhibition of fatty aldehyde catalysis because level of fatty aldehyde (HNE) is inversely correlated with ATP production." (PMID 33537098, 2021). "Thus, low ALDH7A1 expression does not seem to be causally linked to low PPAR activity in other cancers." (PMID 30486822, 2018). "In fact, ALDH7A1 affects a number of genes and factors involved in migration, invasion and metastasis, including transcription factors such as Snail1/2 and can be used to identify tumor-initiating and metastasis-initiating cells in various human carcinomas, including PCa." (PMID 26312765, 2015). "Other worth-mentioning genes and metabolites previously reported in cancer progression are ASS1, CAT, ALDH7A1, arginine, glutamine, BCAAs, and AAAs." (PMID 37999208, 2023). "We therefore evaluated the expression of a panel of epithelial (KRT5, 7, 8, 18, and CDH1), mesenchymal (VIM, FN1, SNAI1, TWIST1, COL1A1, and PRRX1), and cancer stem cell (ALDH1A2, ALDH7A1, CD44, and CCND1) markers in all samples." (PMID 36980717, 2023). "Cancer stem cell markers ALDH1A2, ALDH7A1, CD44, and CCND1 were also upregulated in CTCs compared to HDs." (PMID 32998338, 2020). "Scant literature exists to link ALDH3B1, ALDH7A1, and ALDH18A1 to cancer, although, these studies provide initial evidence that these isoforms favor tumorigenesis." (PMID 31974410, 2020). "(B) Heatmap of the correlation between ALDH7A1 mRNA expression and EGFR RNA and EGFR phosphorylation in all cancer types." (PMID 30486822, 2018).
cancer (continued). "Aldehyde dehydrogenase (ALDH1B1, ALDH2, ALDH3B1, ALDH3B2, ALDH7A1 and ALDH9A1) were involved in the resistance against cyclophosphamide/carboplatin in cancer chemotherapy." (PMID 28225065, 2017). "DU145R80 show a cancer stem cell (CSC)-like signature with a high expression of CSC markers including CD44, CD133, NANOG, Snail, Oct4 and ALDH7A1 and CSC-related genes as STAT3." (PMID 26312765, 2015). "As CSCs are considered to be responsible for drug resistance in many cancer types including PCa, this study aimed to examine whether TKI treatment targeting FGFR would show signs of drug resistance suggested via ALDH7A1 expression." (PMID 33456711, 2021). "Among them are genes involved in cell adhesion/migration processes (PEPD), migratory potential of cancer cells (ACTN1), ECM (LTBP2, PRG4, ADGRL1, CD9), or in metabolic processes (LDHD, ALDH7A1), as well as proto-oncogenes or their ligands/inhibitors (FYN, PPP1R13L)." (PMID 30838002, 2019).
tumor (25 papers, 2014 to 2025). "In conclusion, Tan IIA sensitizes HCC cells to sublethal heat by targeting ALDH7A1, leading to disrupted glycolytic and osmolytic balance, subsequently hindering tumor cell survival and increasing apoptosis." (PMID 41173836, 2025). "Within the tumor tissues, ALDH7A1 expression levels were also lower for patients with nodal metastasis than for those without (P < 0.0257)." (PMID 35613852, 2022). "Conversely, ALDH7A1 expression in tumor tissues and in patients with advanced disease was lower than that in normal tissues and in patients with early-stage disease." (PMID 35613852, 2022). "ALDH7A1 expression was lower in tumor tissues than in normal and adjacent normal tissues from the TCGA database (both P < 0.001)." (PMID 35613852, 2022). "In an in vivo mice model, fewer tumor nodules, bone metastases, and tumor burden were observed upon the ALDH7A1 knockdown." (PMID 34572930, 2021). "The results showed that AGL, SLC16A3, and MIOX were significantly high expressed in tumor samples, whereas HKDC1 and ALDH7A1 were significantly low expressed in tumor samples." (PMID 33991070, 2021). "Immunohistochemical staining demonstrated that ALDH7A1 was highly expressed in primary tumor and bone metastatic samples." (PMID 34572930, 2021). "Here, by targeting ATP production through inhibition of ALDH7A1 and mitochondrial complex I, remarkable regression of tumor size and number in xenograft model as well as KPC mouse model based on Kras mutation has been shown." (PMID 33537098, 2021). "The staining showed significant increase of ALDH7A1 in the tumor of KPC mouse to compare to pancreas of normal mouse." (PMID 33537098, 2021). "ALDH7A1 was generally hypomethylated in normal tissues and actively expressed, whereas hypermethylated and repressed in one third of tumor samples." (PMID 31097695, 2019). "Primary and metastatic PCa also express ALDH7A1 protein, with knockdown of ALDH7A1 reducing the tumor-propagating and metastatic abilities of androgen-independent PCa cells." (PMID 25595909, 2015). "Moreover, it was shown that gossypol and phenformin, which inhibit ALDH7A1 and oxidative phosphorylation, can prevent tumor growth in the KPC mouse model and the xenograft mouse model." (PMID 37686694, 2023). "However, comparison of ALDH7A1 expression in normal and tumor tissues showed that it was lower in tumor tissues than in normal ones." (PMID 37686694, 2023). "Similarly, in tumor tissue, the high-ALDH7A1 group tended to have better progression-free survival outcomes than the low-ALDH7A1 group did, validated by the TCGA database." (PMID 35613852, 2022). "Furthermore, by blocking ALDH7A1 and mitochondrial complex I using gossypol and phenformin, tumor regression was synergistically induced with reduction of ATP level in mice models." (PMID 33537098, 2021). "ALDH7A1 knockdown significantly reduced tumor formation in PDAC." (PMID 33537098, 2021). "Using these data, we asked whether the ALDH7A1 IHC score (tumor-normal) was an informative parameter in the context of well established clinical parameter such as stage for patient survival using multivariate Cox proportional hazards regression analysis." (PMID 30486822, 2018). "Furthermore, the observation that nlz1/NLZ1 which is important in optic fissure closure acts functionally downstream of aldh7a1 is also consistent with the observation that NLZ1 is important in tumor cell division and metastasis." (PMID 25004007, 2014).
tumor (continued). "Using GEPIA2, we noticed that ALDH7A1 mRNA is higher in HCC tissues than normal liver tissues, including tumor-adjacent tissues from TCGA and normal liver tissues from GTEx database, but its mRNA level decreases as tumor stage increases (data not shown)." (PMID 41173836, 2025). "Recent studies have shown that ALDH7A1 is responsible for the NADH generation in the cell membrane, which could regulate the ferroptosis in tumor cells." (PMID 41502512, 2025). "Some tumor type-specific DEs were observed for ALDH1L1, ALDH3B1, ALDH3B2, ALDH4A1 and ALDH7A1." (PMID 29426835, 2018). "Additional studies have reported that ALDH1A1, ALDH7A1, ALDH2 and/or ALDH1A2 are responsible for driving Aldefluor® activity in other tumor types, indicating that the ALDH isoform(s) responsible for Aldefluor® activity may be tumor-specific." (PMID 28937653, 2017). "Interestingly, ALDH7A1, a representative gene with negative methylation-expression correlation (hypermethylated in tumor), showed a gain of repressive H3K9me3 at TSS and a shift of sharp DNA methylation peaks toward TSS, particularly in the highly methylated tumor." (PMID 31097695, 2019).
genetic disorder (5 papers, 2015 to 2023). "In terms of treatability, TSC1-, TSC2-, SLC35A2-, ATP7A-, ALDH7A1-, and MMACHC-related disorders had specific therapeutic regimens and accounted for 18.5% (19/103) of the cases with genetic disorders." (PMID 35330882, 2022).
metabolic disorders (4 papers, 2015 to 2025). "In addition to α-AASA and Δ1-P6C, pipecolic acid (PA) is a non-specific marker of ALDH7A1 deficiency, as increased levels are also found in other metabolic diseases." (PMID 35053812, 2021).
ALDH7A1 also shares sentences with these, for which no sentence is quoted: infection (4 papers); asthma (2); colorectal cancer (2); esophageal squamous cell carcinoma (2); glioblastoma (2); infantile spasms (2); liver disease (2); lymph node metastasis (2); Seizure (2); -dependent (1); adenocarcinoma (1); adrenocortical carcinomas (1); adrenocortical tumors (1); Angelman syndrome (1); autism spectrum disorder (1); autoimmune hepatitis (1); brain tumors (1); cardiac disease (1); cardiac ischemia (1); chronic heart failure (1); CLN7 disease (1); deficiency (1); dementia (1); DHPR deficiency (1); epilepsy syndrome (1); Epileptic spasm (1); Glucose intolerance (1); glycine encephalopathy (1); hemorrhagic stroke (1); hereditary spastic paraplegia (1).
A further 27 diseases each share a sentence with ALDH7A1 in 1 paper.